CD4 (CD4 molecule)
Diseases named in the same sentence as CD4 in open-access papers (continued):
Sharing a sentence is not in itself a finding about the gene and the disease.
autoimmune disease (continued). "In particular, examination of CD4+ Teff in autoimmune disease is the best demonstration of the functional power of T cells harboring lower affinity TCRs." (PMID 33120989, 2020). "Addressing these questions will be paramount to develop better treatments for CD4+ T cell-driven autoimmune diseases." (PMID 32106536, 2020). "For instance, patients with MS and psoriasis show increased numbers of memory CD4+ T cells as compared with healthy individuals, suggesting that memory CD4+ T cell are critical mediators of autoimmune disease." (PMID 32106536, 2020). "There is a high expression of CXCR4 on CD4+ T cells, contributing to the migration of CD4+ T cells to pancreatic islets and destruction of β cells in T1D and other autoimmune diseases." (PMID 32878069, 2020). "Recent studies have identified that miRNAs regulate the pathogenesis of autoimmune diseases through the modulation of CD4+ T cell differentiation." (PMID 32269577, 2020). "While much is known about the effector function of Th cells in combating pathogens and promoting autoimmune diseases, the roles and biology of memory CD4+ Th cells are complex and less well understood." (PMID 32106536, 2020). "In the past, RA was considered as an autoimmune disease driven by pro-inflammatory CD4+IFN-γ+ (Th1) T helper cells which predominate over the CD4+IL-4+ (Th2) subset that exerts regulatory functions." (PMID 32358783, 2020). "Interleukin 27 (IL-27) plays diverse immune regulatory roles in autoimmune disorders and promotes the generation of IL-10–producing CD4+ T cells characterized by producing the immunosuppressive cytokine IL-10." (PMID 32849596, 2020). "Treg, a special subset of CD4+ T cells, is essential in the regulation of immune-mediated diseases such as autoimmune diseases, tumorigenesis and some infections." (PMID 33584256, 2020). "It is well-established that CD4+ T cells play a pivotal role in the pathogenesis of several autoimmune diseases." (PMID 32977850, 2020). "The imbalance between regulatory CD4+ T (Treg) and effector CD4+ T-cells (Teffs, such as Th17 and Th1) has been widely accepted to be the core mechanism of autoimmune diseases including AU." (PMID 33281814, 2020). "The adoptive transfer of CD4+CD25+ T cells prevented autoimmune disease development induced by CD4+CD25− T cells, and the suppressive function was defined later as dependent on the expression of transcription factor forkhead box P3 (Foxp3)." (PMID 32397343, 2020). "Regulatory T cells (Tregs) are a kind of CD4+ T cells that inhibit immunopathology or autoimmune disease in vivo by influencing the activity of other cell types." (PMID 33123120, 2020). "Treg cells are a suppressive subset of CD4+ T subsets important for the regulation of immune responses in various autoimmune diseases." (PMID 33643223, 2020). "The presence of CD4+ CTL at the site of inflammation has been reported in several autoimmune diseases." (PMID 30915067, 2019). "We investigated the classical CD4+CD25+Foxp3+ Treg phenotype which was widely used in autoimmune diseases, but also supplied novel evidence of Treg subpopulations in different clinical stages of HT and their associations with clinical features." (PMID 31214258, 2019). "As no immunosuppressive agent was used, we presumed that the altered CD4+T cells related to the nature of the autoimmune disease and the infections." (PMID 30994732, 2019). "Manipulating effector or regulatory CD4+ T cells responses is a promising immunotherapy strategy for, respectively, chronical viral infections and cancer, or severe autoimmune diseases and transplantation." (PMID 31156634, 2019). "In many autoimmune diseases, HLA class II molecules are expressed on APCs and present self-antigens to CD4+ T cells." (PMID 31817224, 2019). "In autoimmune diseases, self-antigen recognition disorders and dysfunction of immune tolerance results in immune attack of CD4+ or CD8+ T cells to self-antigens." (PMID 30988391, 2019).
autoimmune disease (continued). "Such effector/memory CD4+ T cell subsets have been shown to be important in promoting idiopathic and experimental autoimmune disease." (PMID 31555266, 2019). "Both these cell types have been reported to undergo cytokine reprogramming during conditions of heightened chronic inflammation and a shifting cytokine milieu that develop during a number of CD4 T cell-mediated autoimmune diseases." (PMID 31616418, 2019). "CD4+ T cells are crucial for directing appropriate immune responses and involved in disease progression in autoimmune diseases and other diseases." (PMID 31443687, 2019). "Another recent study showed that CD4+CD25low/−Foxp3+ T cells represent a subpopulation of Tregs derived from CD4+CD25highFoxp3+ T cells in autoimmune diseases." (PMID 30842769, 2019). "Effector/memory CD4+ T cells are the main drivers of autoimmune diseases due to their persistence and diverse contributions to pathology." (PMID 31555266, 2019). "Recently, a population of CD4+CD39+Foxp3+ T cells was identified as having a regulatory function in the autoimmune disease model." (PMID 30622237, 2019). "Either induction of endogenous CD4+CD25+ Tregs or adoptive transfer of exogenous Tregs prevents autoimmune diseases and allograft rejection in many animal models." (PMID 30988670, 2019). "We identified 15,289 differentially methylated sites between multiple-autoimmune disease patients and controls in CD4+ T cells." (PMID 31024609, 2019). "In autoimmune diseases, autoreactive CD4+ T cells show elevated metabolism with increased glycolysis and mitochondrial respiration." (PMID 31057554, 2019). "Multiple sclerosis is an autoimmune disease of the central nervous system (CNS) mediated by CD4+ T cells and modeled via experimental autoimmune encephalomyelitis (EAE)." (PMID 30941147, 2019). "CD4 T cells confer their pathogenicity by two pathways in autoimmune diseases and chronic inflammation." (PMID 31998318, 2019). "Treg cell numbers and function have also been implicated in complex autoimmune diseases including rheumatoid arthritis (RA) and JIA, and in fact the first data on CD4+ Treg cells in human chronic arthritis comes from JIA patients." (PMID 30792714, 2019). "Th17 cells, which is considered as a subset of CD4+ T cells, have recently been found to play a critical role in the development of autoimmune disease (Bettelli, Korn, Oukka, & Kuchroo, 2008; Kurts, 2008)." (PMID 31742934, 2019). "Autoimmune disease in Malt1-PD mice was previously explained by a disrupted balance between effector CD4+ T cells and the number of Tregs." (PMID 31474984, 2019). "Compelling experimental data from mouse models indicate that adoptive immunotherapy harnessing immunosuppressive properties of CD4+ regulatory T cells is a promising therapeutic strategy against autoimmune diseases and GVHD or allograft rejection." (PMID 31156634, 2019). "Due to their multiple functions in immunity and immune tolerance, targeting CD4+ T cells has important clinical applications to treat cancer and chronic viral diseases, or to induce tolerance in autoimmune diseases and allograft." (PMID 31156634, 2019). "Androgens decrease the Th1 differentiation of CD4+ T cells via inhibiting IL-12 signaling, which in turn mitigates CD4+ responses in autoimmune disease." (PMID 31275761, 2019). "As an autoantigen, Proteoglycans can stimulate sequential immune reactions via activation of CD4+ T cells, which is observed in autoimmune disease of rheumatoid arthritis." (PMID 30733969, 2019). "We here provide an overview and focus on the role of the different types of HDACs in CD4+ Teff cells and Treg cells, and explore the potential of specific HDACi as a therapeutic strategy for the treatment of autoimmune diseases, in specific oJIA and pJIA." (PMID 30792714, 2019). "CD4+ T helper (TH) cells play a central role in orchestrating adaptive immune response to pathogens and also contribute to autoimmune diseases." (PMID 32010133, 2019).
autoimmune disease (continued). "CD4+ T helper (TH) cells are critical for protective adaptive immunity against pathogens, and they also contribute to the pathogenesis of autoimmune diseases." (PMID 32010133, 2019). "Before and in line with literature, we had clearly detected CNS-resident Tregs in mice diseased with experimental autoimmune disease, and at least a few CD4+ FOXP3+ cells were found in early active brain lesions of human MS patients." (PMID 32010141, 2019). "Our previous study showed that after long-term co-culture, MSCs interfere with the functional activity of Th17 cells, a CD4+ T cell population that plays an important role in the development of autoimmune diseases, such as RA." (PMID 31370879, 2019). "The concept of regulatory T cells was revisited in 1995 when the group of Sakaguchi described a population of CD4+ CD25+ T cells capable of preventing the development of several autoimmune diseases in mice." (PMID 30915067, 2019). "Although long neglected in autoimmune diseases compared to CD4+ T-cells, CD8+ T-cells are equipped with different capacities by which they can contribute to the inflammatory process." (PMID 31143175, 2019). "It induces the differentiation of naive CD4 T-cells to IL-17 which plays key roles in pathogenesis of autoimmune diseases." (PMID 31409341, 2019). "Overall, most studies suggest a pro-inflammatory role for SIRT1 in CD4+ T cells, and especially Treg cells, in the setting of autoimmune diseases." (PMID 30792714, 2019). "This all is in line with the fact that fully developed eLFs with FDCs, compartmentation into a light and dark zone, an excess of GC-B cells over TFHs as well as the presence of “true”, i.e., active CD4+CXCR5+BCL-6+ TFHs are rare in human autoimmune diseases." (PMID 32010141, 2019). "Other studies focused on T cells and worked out that sodium chloride drives autoimmune diseases by an induction of interleukin (IL)-17-producing CD4+ helper T cells (TH17 cells)." (PMID 30589884, 2018). "Increasing evidence supports the earlier findings that myocarditis is an autoimmune disease that involves the participation of CD4+ T cells." (PMID 29854842, 2018). "In mice, therapeutic approaches using Foxp3 gene-transduced CD4+ Tregs have been successful in the induction of tolerance in graft-versus-host disease and some autoimmune diseases." (PMID 29535721, 2018). "Hhph-1 showed higher Foxp3 delivery into the nucleus compared with Hph-1 for converting CD4+ T cells to suppressor cells to inhibit autoimmune diseases in mice." (PMID 29518031, 2018). "Elevated sIL-6R by auto-reactive CD4+ T cells contributes to autoimmune disease development via conferring IL-6 responsiveness as well as blocking Treg development." (PMID 30327657, 2018). "Next, intrathymic differentiation/maturation of CD4+ nTregs involved in the maintenance of self-tolerance and prevention of autoimmune disorders was also examined." (PMID 30086167, 2018). "Appropriate CD4+ T cell activation is crucially important for adaptive immune responses and autoimmunity, but hyper-activation of these cells results in autoimmune diseases." (PMID 29434598, 2018). "To identify the molecular mechanisms resulting in suppression of CNS-specific autoimmune disease, we sorted CD4+ T cells from the intestinal lamina propria of control and CR diet-fed mice and determined their cytokine expression profile by qPCR screens." (PMID 29993025, 2018). "As an autoimmune disease, MG is characterized by the overproduction of AChR antibodies; the disequilibrium of B cells and Foxp3+ CD4+ Treg cells is involved in the overproduction of AChR antibodies." (PMID 30483222, 2018). "Experimental autoimmune encephalomyelitis is an activated CD4+ T cell-mediated autoimmune disease model." (PMID 29434598, 2018). "Interleukin-2 (IL-2) is critical for maintaining the function of the CD4+ regulatory T cells (Tregs), which in turn regulate autoreactive CD4+ effector T cells (Teffs) to prevent autoimmune diseases, such as T1D." (PMID 29867762, 2018).
autoimmune disease (continued). "CD4+ T cells are known to play an important role in the development of autoimmune diseases, with their inhibition leading to the suppression of disease development." (PMID 29568705, 2018). "Recently, ASMase was proposed as a novel target for the therapy of human autoimmune diseases, since it shows a pivotal role in regulation of human CD4 + T-cell activation and responses." (PMID 29449691, 2018). "Increased local salt concentrations boosted the induction of murine and human CD4+ T cells differentiation into Th17 phenotype and thereby drives autoimmune diseases." (PMID 29614818, 2018). "During immune homeostasis, Tregs prevent autoimmune diseases and inflammation and constitute approximately 5–10% of CD4+ T cells in rodents." (PMID 30210499, 2018). "We tested this in an EAE model, which is a widely used mouse model that mimics chronic MS in humans and is considered a CD4+ Th1-mediated autoimmune disease." (PMID 29727445, 2018). "On the other side, IL-9 is a cytokine produced primarily by CD4+ Th9 cells and is generally reported to mediate allergic and autoimmune diseases." (PMID 29967565, 2018). "Estrogen influences not only development but also various functions of T cells, in particular CD4 T cells including activation, cytokine production differentiation and regulatory functions with impact on physiology and autoimmune diseases." (PMID 30337927, 2018). "EAE is a typical Th17-related autoimmune disease modeled in mice, and Rfx1 expression was decreased significantly in CD4+ T cells from EAE mice compared with wild type (WT) mice." (PMID 29422534, 2018). "Experimental autoimmune encephalomyelitis, a T cell-mediated autoimmune disease, is a chronic and multiphasic autoimmune inflammatory disorder of the CNS, and is thought to be triggered by myelin-specific CD4+ Th1 and Th17 cells." (PMID 29403497, 2018). "Macrophages and monocytes play a critical role in the pathogenesis of several autoimmune diseases by acting as key producers of mediators of inflammation further supporting the development of CD4+ and CD8+ pro-inflammatory cells." (PMID 29574654, 2018). "Female gender and hormonal influences regulate FoxP3 expression and therefore are critical in the physiology of regulatory CD4 T cells and the gender bias of autoimmune disease." (PMID 30337927, 2018). "Multiple sclerosis (MS) is a CD4 T cell-modulated autoimmune disease dependent on myelin-based protein (MBP), a protein discovered uniquely in myelin sheaths." (PMID 30013600, 2018). "The CD4+ T cell is viewed as the initiator of T1D as dysregulation of CD4+ antigen-recognition drives the autoimmune disease." (PMID 30485278, 2018). "CD4+ helper T cells are crucially involved in the progressions of various autoimmune diseases including MS and EAE." (PMID 30079025, 2018). "In the adult population, the presence of ILD correlated positively with autoimmune disease and markedly lower CD4+ T cell, naïve CD4+ T cell, and naïve and switched memory B-cell counts." (PMID 30147696, 2018). "Currently, MS is one of the most prevalent autoimmune diseases mediated by CD4 T cells in the central nervous system (CNS)." (PMID 30013600, 2018). "Retinoic acid-related orphan receptor gamma (RORγ) plays pivotal roles in autoimmune diseases by controlling the lineage of interleukin 17 (IL-17)-producing CD4+ T cells (Th17 cells)." (PMID 30478402, 2018). "Although CD8 + T cells have been shown to be involved in the development of autoimmune diseases such as MS and EAE, it is generally accepted that over-activation of self-Ag pathogenic CD4+ T cells is the direct cause of these diseases." (PMID 30327657, 2018). "Defects in Egr2 and 3 lead to the development of autoimmune disease with high levels of IFN-γ–producing CD4 T cells." (PMID 28455436, 2017).
autoimmune disease (continued). "Th17 cells, a key player in autoimmune diseases and antibiosis, are differentiated from naïve T cells (CD4+) stimulated by IL-6, TGF-β, IL-1β, IL-21 and IL-23 and release IL-17A, IL-17F, IL-21 and IL-22." (PMID 28899359, 2017). "There is a pressing need to develop specific immunotherapies for autoimmune diseases, and considerable attention is focused on the potential beneficial effects of peptides recognized by auto-reactive CD4 T cells." (PMID 28455817, 2017). "IL-17 is a proinflammatory cytokine secreted by Th17 cells, which comprise a distinct subset of CD4+ T cells that play a role in autoimmune disease." (PMID 28577559, 2017). "The impaired function of CD4+CD25+Foxp3+ Tregs has been confirmed to contribute to the pathogenesis of autoimmune diseases including AA." (PMID 28683082, 2017). "Aire -/- mice are an established mouse model of autoimmune disease that acquire CD4 T cell-mediated lacrimal gland exocrinopathy, aqueous tear deficiency, and ocular surface damage similar to that observed in SS patients." (PMID 28926640, 2017). "Enrichment of GWAS variants in cell‐type‐specific promoters marked by histone‐3 lysine‐4 trimethylation (H3K4me3), confirmed the importance of CD4+ T‐cell subsets in a number of autoimmune disorders, including T1D and RA." (PMID 28718505, 2017). "We expect that those PTPs that regulate T helper polarisation will constitute potential targets for intervening CD4 T cell immune responses in order to generate new therapies for the treatment of autoimmune diseases." (PMID 28393080, 2017). "Type 1 diabetes is an autoimmune disease in which insulin-producing β-cells are destroyed by CD4+ and CD8+ T cells and CAMφs." (PMID 29249872, 2017). "CD4+ T cells are essential to an immune response, and Th1 and Th17 cells have been extensively studied to understand inflammation and autoimmune diseases." (PMID 28241881, 2017). "Class I associations to RA, T1D, and other autoimmune diseases suggest that CD8+ cytotoxic cells are involved in disease pathogenesis, as well as CD4+ helper T cells." (PMID 28449694, 2017). "Inhibiting differentiation of naïve CD4+ T cells into proinflammatory Th1 and Th17 cells helps to mitigate autoimmune disease." (PMID 28241881, 2017). "CD4+ T cells that co-express IL-17 and IFN-γ have been reported to be associated with TB disease severity and are increased in certain autoimmune diseases." (PMID 29075255, 2017). "Since IL-10 is postulated to function as a negative regulator in some autoimmune diseases, the intracellular IL-10 by CD4+ T cells and Tregs was also investigated." (PMID 29312539, 2017). "The induction of endogenous CD4+CD25+ Tregs or adoptive transfer of exogenous Tregs prevents autoimmune diseases and allograft rejection in many animal models." (PMID 28947964, 2017). "We here report eQTL mapping in purified CD4+ and CD8+ T cells and reveal multiple effects on regulation of genes associated with autoimmune diseases." (PMID 28248954, 2017). "Detection of an antigen-specific CD4 T cells is also a major challenge in the context of autoimmune diseases." (PMID 29065175, 2017). "By analyzing eQTLs in CD4+ and CD8+ T cells, essential elements of adaptive immune response, we identified both cis- and trans-acting SNPs in genes associated with several autoimmune diseases." (PMID 28248954, 2017). "It was found that the number of CD4+CD25+Treg cells decreased in the Foxp3 gene knockout or mutation mice, greatly increasing the incidence of autoimmune diseases." (PMID 29156761, 2017). "Either induction of endogenous CD4+CD25+ Tregs or adoptive transfer of exogenous Tregs prevents autoimmune diseases and allograft rejection in animal models." (PMID 29167674, 2017). "Thymus-derived natural Foxp3+ CD4+ regulatory T cells (nTregs) play a key role in maintaining immune tolerance and preventing autoimmune disease." (PMID 28690613, 2017).